BCDIN3D (BCDIN3 domain containing RNA methyltransferase)
Description:
O-methyltransferase that specifically monomethylates 5'-monophosphate of cytoplasmic histidyl tRNA (tRNA(His)), acting as a capping enzyme by protecting tRNA(His) from cleavage by DICER1. Also able, with less efficiently, to methylate the 5' monophosphate of a subset of pre-miRNAs, acting as a negative regulator of miRNA processing. The 5' monophosphate of pre-miRNAs is recognized by DICER1 and is required for pre-miRNAs processing: methylation at this position reduces the processing of pre-miRNAs by DICER1. Was also reported to mediate dimethylation of pre-miR-145; however dimethylation cannot be reproduced by another group which observes a monomethylation of pre-miR-145.
Tractability: Small molecule: a structure with a bound ligand is known. Antibody: its Gene Ontology location is reachable by antibodies, with high confidence. PROTAC: ubiquitination databases record sites on it.
Target class: Enzyme; Transferase
Gene: Protein-coding gene on chromosome 12 (49,836,043 to 49,843,106, reverse strand). Ensembl gene ENSG00000186666.
Subcellular location: Cytoplasm
Subcellular location (Human Protein Atlas): Cytosol; Nucleoplasm; Plasma membrane
Pathways (Reactome):
Gene expression (Transcription): MicroRNA (miRNA) biogenesis
Gene Ontology:
Molecular function: O-methyltransferase activity; pre-miRNA binding; protein binding; RNA methyltransferase activity; small RNA 2'-O-methyltransferase activity; tRNA methyltransferase activity; methyltransferase activity
Biological process: negative regulation of pre-miRNA processing; pre-miRNA processing; RNA methylation; tRNA methylation; miRNA metabolic process
Cellular component: cytoplasm; cytosol
Genetic constraint (gnomAD): Loss-of-function variants: 18 observed, 24.98 expected, observed/expected ratio (o/e) 0.72, 90% interval 0.5 to 1.07. The upper end of that interval is the gene's LOEUF score, 1.07, which puts it in group 4 of 6, group 1 being the genes least tolerant of losing a copy. Missense variants: 331 observed, 387.89 expected, observed/expected ratio (o/e) 0.85, 90% interval 0.78 to 0.94. Synonymous variants: 127 observed, 152.16 expected, observed/expected ratio (o/e) 0.83, 90% interval 0.72 to 0.97.
Homologues: Orthologues: chimpanzee BCDIN3D (99% identical), pig BCDIN3D (88% identical), dog BCDIN3D (87% identical), guinea pig BCDIN3D (79% identical), rabbit BCDIN3D (79% identical), mouse Bcdin3d (77% identical), rat Bcdin3d (77% identical), tropical clawed frog bcdin3d (51% identical), zebrafish bcdin3d (44% identical), Drosophila melanogaster CG11342 (30% identical). Paralogues in human: MEPCE (25% identical).
Diseases named in the same sentence as BCDIN3D in open-access papers:
BCDIN3D is named in the same sentence as 14 diseases in open-access papers, as found by Europe PMC text mining. Sharing a sentence is not in itself a finding about the gene and the disease. The quoted sentences say what the papers report.
breast carcinoma (11 papers, 2016 to 2025). "In a cohort of 227 breast cancer patients, tumor levels of BCDIN3D was associated with lower disease‐free survival." (PMID 36617746, 2023). "BCDIN3D is overexpressed in breast cancer, which is associated with poor prognosis of breast cancers." (PMID 30127802, 2018). "This review discusses recent reports on BCDIN3D and the possible association between 5′-phosphate monomethylation of tRNAHis and the tumorigenic phenotype of breast cancer." (PMID 30127802, 2018). "We describe herein that a specific tRNA for histidine (tRNAHis) is now identified as a primary target of BCDIN3D and discuss the association between the tumorigenic phenotype of breast cancer and the methylation of tRNAHis by BCDIN3D." (PMID 30127802, 2018). "BCDIN3D mRNA overexpression has been reported in human breast cancer cells, which is associated with cellular invasion and poor prognosis in triple-negative breast cancer." (PMID 30127802, 2018). "Interestingly, the up‐regulated BCDIN3 domain containing RNA methyltransferase gene (BCDIN3D) has been clearly linked to breast cancer progression, via down‐regulation of tumor suppressor miRNAs." (PMID 36617746, 2023). "Elevated expression of BCDIN3D has been associated with poor prognosis in breast cancer." (PMID 31145769, 2019). "BCDIN3 is found to be overexpressed in breast cancer; however, the role of BCDIN3D-mediated tRNA 5′-monomethylation in the tumorigenic characteristics of breast cancer cells is not yet fully understood." (PMID 38476632, 2024). "Studies have identified that the distribution of BCDIN3 Domain Containing RNA Methyltransferase (BCDIN3D), a RNA methylate in type II diabetes, is correlated with breast cancer prognosis." (PMID 35008539, 2021). "Consistently, knockdown of BCDIN3D leads to lower pre-miR-145 and concomitantly increased mature miR-145 levels in breast cancer cells, which suppresses their proliferative and invasive ability." (PMID 32209098, 2020). "The molecular basis of involvement of BCDIN3D in the tumorigenic phenotype of breast cancer has remained elusive." (PMID 30127802, 2018). "Elucidation of the regulatory mechanism of specific pre-miRNA (di)methylation process by BCDIN3D in breast cancer cells awaits further study." (PMID 30127802, 2018). "Then we analyzed the relationship between BCDIN3D expression and survival according to the different breast cancer subtypes." (PMID 27259993, 2016). "Importantly, BCDIN3D depletion in breast cancer cells increases miRNA-145 mature isoform and reduces cell invasiveness." (PMID 33564819, 2021). "Knockdown BCDIN3D suppresses breast cancer growth by modulating mitochondrial respiration." (PMID 35008539, 2021). "However, further studies are needed to understand the relative contribution of BCDIN3D tRNA methylation activity to breast cancer." (PMID 33564819, 2021). "In total, this work also suggested O-methylation of miRNAs represents an important modulation of ncRNA and the 2′-O-methylation methyltransferase BCDIN3D might serve as a putative target in treatment of breast cancer." (PMID 32209098, 2020). "BCDIN3D depletion in breast cancer cells abolishes their tumorigenic phenotypes." (PMID 31145769, 2019). "In addition, BCDIN3D mRNA is overexpressed in human breast cancer cells and elevated expression of BCDIN3D mRNA has been associated with poor prognosis in breast cancer." (PMID 31145769, 2019). "Under certain biological process or specific conditions in breast cancer cells, BCDIN3D might recognize specific pre-miRNAs, such as pre-miR145, through the regulatory factors which assist BCDIN3D in recognizing specific RNA species." (PMID 30127802, 2018). "Therefore, it was proposed that BCDIN3D promotes the cellular invasion of breast cancer cells by downregulating tumor suppressor miRNAs through dimethylation of the 5′-phosphate group of the corresponding pre-miRNAs." (PMID 30127802, 2018).
breast carcinoma (continued). "Thus, the mechanisms by which BCDIN3D recognizes only a specific group of pre-miRNAs and downregulates mature miRNAs in breast cancer cells are unclear." (PMID 30127802, 2018). "Our study is the first to evaluate the prognostic value of BCDIN3D in breast cancer patients." (PMID 27259993, 2016). "BCDIN3D has been implicated in breast cancer, as its depletion significantly decreases transformation and invasion of MDA-MB-231 breast cancer cells in vitro and in vivo, and its overexpression correlates with poor prognosis in breast cancer, especially in triple-negative subtypes." (PMID 38263329, 2024). "Hence, BCDIN3D could serve as a link between alcohol consumption and breast cancer tumorigenesis and survival." (PMID 36617746, 2023). "Future studies are required to understand whether methylation of the 5′-phosphate group of tRNAHis by BCDIN3D is involved in the tumorigenic phenotype of breast cancer and other cancers and to potentially elucidate the unknown functions of tRNAs, beyond their established functions." (PMID 30127802, 2018). "Although BCDIN3D has been shown to increasetumorigenic phenotypes and invasiveness in MDA-MB-231 cells, its the clinical implications in breast cancer remain unclear." (PMID 27259993, 2016).
Obesity (3 papers, 2010 to 2024). Accumulation of substantial excess body fat. "Given the association of the BCDIN3D locus with obesity and type II diabetes, we decided to focus our mechanistic efforts on this mRNA." (PMID 38263329, 2024). "In addition, the BCDIN3D locus is associated with obesity and type II diabetes, suggesting a broader but unknown function in human diseases." (PMID 38263329, 2024). "Leaving the hypothesis-free approach and focussing on known GWAS-based candidate markers, we were able to substantiate another four loci (NEGR1, SEC16B, BDNF and BCDIN3D) of the 16 obesity loci previously detected in GWAS." (PMID 20421936, 2010). "Thus, we demonstrate that the currently known major common variants related to obesity overlap to a substantial degree between children and adults confirming previous observations for FTO, MC4R, TMEM18, NEGR1 and extending this observation to SEC16B, BDNF and BCDIN3D;." (PMID 20421936, 2010).
cervical cancer (2 papers, 2021 to 2022). A primary or metastatic malignant neoplasm involving the cervix. "Downregulation of miR-195-3p expression in cervical cancer tissues is linked to adverse prognosis of the patients; miR-195-3p overexpression impedes cancer cell growth by targeting BCDIN3D." (PMID 34585634, 2021). "For example, miR-195-3p inhibited cervical cancer cell proliferation by targeting BCDIN3D, and reversed CCL4-enhanced VEGF-C expression in Oral Squamous Cell Carcinoma." (PMID 34980201, 2022).
female sterility (1 paper, 2019). "To gain insight into the molecular mechanism by which ovary-specific knockdown of BCDIN3D causes female sterility, we performed high-throughput sequencing of ovary small RNAs (sRNA-seq) using three biological replicates for each genotype." (PMID 31145769, 2019). "Ovary-specific depletion of BCDIN3D caused complete female sterility." (PMID 31145769, 2019). "Dysregulation of these pathways may cause the female sterility by ovary-specific BCDIN3D knockdown." (PMID 31145769, 2019). "In this study, we show that ovary-specific knockdown of Drosophila BCDIN3D causes female sterility without clear morphological defect in ovaries." (PMID 31145769, 2019).
invasive ductal breast carcinoma (1 paper, 2016). The most common type of invasive breast carcinoma, accounting for approximately 70% of breast carcinomas. "We screened for BCDIN3D using tissue microarrays constructed from 250 patients who were histologically confirmed to have invasive ductal breast carcinoma at the Fudan University Shanghai Cancer Center." (PMID 27259993, 2016).
triple-negative breast carcinoma (1 paper, 2016). An invasive breast carcinoma which is negative for expression of estrogen receptor (ER), progesterone receptor (PR), and human epidermal growth factor receptor 2 (HER2). "Furthermore, as more future basic and clinical studies uncover the underlying mechanism in this pattern, BCDIN3D could emerge as a desperately needed therapeutic targetin triple-negative breast cancer." (PMID 27259993, 2016). "The prognostic value of BCDIN3D was most significant in triple-negative breast cancer (TNBC) patients (P = 0.007)." (PMID 27259993, 2016). "In conclusion, our results associate, for the first time, higher BCDIN3D levels with worse DFS, especially in triple-negative breast cancer population, which suggests its potential use as a predictive biomarker." (PMID 27259993, 2016).
viral infection (1 paper, 2024). "Finally, future experiments will also be needed to determine whether BCDIN3D methylation and its RNA targets regulate other noncanonical functions of EPRS, such as the cellular responses to DNA damage, IFN-γ, viral infection and metabolic status." (PMID 38263329, 2024).
cancer (4 papers, 2018 to 2025). A tumor composed of atypical neoplastic, often pleomorphic cells that invade other tissues. "Given the known functions of PRKAG1-interacting proteins (e.g., BCDIN3D, KBTBD4, CUL3) in cell cycle regulation, we evaluated the association between PRKAG1 expression and cancer-related pathways using gene set variation analysis (GSVA)." (PMID 40958861, 2025). "In the future, it will be of upmost importance to investigate the biological function of tRNAHis 3’ fragments, including in contexts where BCDIN3D function may be of clinical importance, such as cancer and metabolic disease." (PMID 31329584, 2019).
tumor (4 papers, 2016 to 2023). "Recent studies have revealed m6A methylation components can act as tumor-associated factors, including “writers” (METTL3/14, WTAP and KIAA1429), “erasers” (FTO and ALKBH5), and “readers” (YTHDF1/2/3, HNRNPA2B1, BCDIN3D)." (PMID 33791305, 2021). "The functions of BCDIN3D, ZNF668, and GNPTG in tumor are poorly studied." (PMID 36470859, 2022).
BCDIN3D also shares sentences with these, for which no sentence is quoted: Leigh syndrome (1 paper); lung carcinoma (1); metabolic disease (1); Oral Squamous Cell Carcinoma (1); type II diabetes (1).